ATG7 (autophagy related 7)
Diseases named in the same sentence as ATG7 in open-access papers (continued):
Sharing a sentence is not in itself a finding about the gene and the disease.
atherosclerosis (16 papers, 2017 to 2025). A disease characterized by the build-up of fatty material and calcium deposition in the arterial wall resulting in partial or complete occlusion of the arterial lumen. "Macrophage-specific ATG7-deficient mice exhibited increased susceptibility to atherosclerosis by increasing macrophage LDL uptake and foam cell formation." (PMID 35096837, 2021). "Atherosclerosis development was severely impaired in mice with T cell-specific Atg7 deficiency which can be explained by low levels of serum cholesterol and low numbers of CD4+ T cells, CD8+ T cells and NKT cells." (PMID 30619297, 2018). "Since we were interested in the effect of T cell-specific Atg7 deficiency on the development of diet-induced advanced atherosclerosis we quantified atherosclerotic lesion size in the aortic root after 22 weeks of WTD." (PMID 30619297, 2018). "Next, we assessed whether the progression of atherosclerosis and plaque instability observed in ApoE−/− mice deleted for Atg7 in VSMCs was associated with dysfunctional and impaired mitochondrial quality control." (PMID 30741928, 2019). "This means KMUP-1 possesses a proautophagy effect by targeting Atg7 protein activation against atherosclerosis in HFD-fed ApoE-KO mice." (PMID 41194853, 2025). "Deletion of key autophagy-related genes (e.g., Atg5, Atg7, Atg14) in mouse macrophages accelerates the development of atherosclerosis as evidenced by increased apoptosis and necrotic cores." (PMID 39766264, 2024). "ATG7 has been reported as an indispensable participant in the process of autophagy in atherosclerosis." (PMID 36180886, 2022). "Recent experimental studies sparked the involvement of autophagy-related 7 (ATG7) in the development of atherosclerosis." (PMID 35777002, 2022). "In this study, by using an in vivo model of atherosclerosis with a deletion of the autophagy gene Atg7 in VSMCs, we provide evidence that a worsened apoptotic and inflammatory phenotype of the plaques occurred compared with their wild-type counterparts." (PMID 30741928, 2019). "In summary, as shown in the schematic diagram, our study demonstrated that CARMN knockdown suppressed CSNK1A1 expression, thereby promoting VSMC-derived foam cell formation and atherosclerosis via the transcriptional downregulation of autophagy mediated by the AKT/ATG7 pathway." (PMID 41213929, 2025). "Notably, KMUP-1 co- and posttreatment rescued the impaired autophagy flux by significantly increasing the Atg7 level; this effect offers the antiapoptotic function to reverse atherosclerosis." (PMID 41194853, 2025). "In addition, ATG7 gene deletion in VSMCs was also found to inhibit autophagy and favor atherosclerosis and aortic aneurysm induced by high cholesterol levels, with subsequent reduced survival because of aortic rupture." (PMID 34754985, 2021). "For a translation into a clinical setting in which cardiovascular patients could be treated with pharmacological autophagy inhibitors, it would be interesting to knock-out Atg7 using an inducible Cre mouse model in mice with pre-developed atherosclerosis." (PMID 30619297, 2018). "Thus, inhibiting the AKT/ATG7 pathway in VSMCs may be an effective strategy for treating atherosclerosis." (PMID 41213929, 2025). "In the human aortic VSMC model of atherosclerosis, the lncRNA RASSF8 antisense RNA 1 (RASSF8-AS1) sponges miR-188-3p to elevate autophagy-related 7 (ATG7) expression and induce autophagy." (PMID 40823532, 2025). "Taken together, the DSVs in ATG7 gene identified in AMI patients may increase or decrease ATG7 levels, which lead to defective or excessive autophagic activity, contributing to the development of atherosclerosis and AMI." (PMID 30407747, 2018).
colitis (16 papers, 2012 to 2025). Inflammation of the colon. "Here, we report that Atg7 deficiency in intestinal epithelial cells shapes the intestinal microbiota leading to an associated limitation of colitis induced by Citrobacter rodentium infection." (PMID 39971913, 2025). "Not only that, mice with myeloid-specific deletion of ATG7 had increased susceptibility to colitis and more severe symptoms." (PMID 40842999, 2025). "Paradoxically, while CD4+ T cell‐specific Atg7 deficiency exacerbated colitis, ATG7 expression was upregulated in active IBD patients." (PMID 40887825, 2025). "In summary, these findings suggested that deficiency of Atg7 worsens TNBS‐induced colitis by enhancing Th1 immune responses and hindering Treg cell development." (PMID 40887825, 2025). "Further studies have shown that the exacerbation of colitis symptoms in ATG7 conditional knockout (cKO) mice is associated with abnormal bacterial flora composition, dysregulated expression of antimicrobial peptides, and inhibition of colonic mucin secretion." (PMID 40842999, 2025). "Genetic association studies suggest that LRRK2/MUC19 and ATG7 deficiency aggravates intestinal inflammation in mouse models of colitis." (PMID 33904657, 2021). "Deletion of Atg7 in myeloid cells by using LysM-Cre mice increased susceptibility to dextran sodium sulfate–induced colitis." (PMID 32513210, 2020). "Another group showed that mice with myeloid cell-specific deletion of ATG7 exhibited increased susceptibility to experimental colitis accompanied with increased colonic inflammation." (PMID 30669622, 2019). "In summary, we have analysed intestinal epithelial-specific Atg7-deficient mice and challenged them with mouse models of experimentally induced colitis." (PMID 22291845, 2012). "Further studies have to investigate why stem cells, although they are long living, seem to be unaffected by Atg7 deficiency and if other environmental triggers render Atg7IEC-KO mice more susceptible to experimentally induced colitis." (PMID 22291845, 2012). "Notably, both Atg7ΔCD4 mice that induced by TNBS rectal administration and Atg7ΔCD4CD45RBhighCD4+ T cell‐reconstituted Rag1−/− mice, displayed more severe colitis, suggesting that Atg7 deficiency disrupts Th1/Treg cell‐mediated mucosal immunity." (PMID 40887825, 2025). "Since mice deficient in Atg7 produced through LysM-Cre or Cx3cr1Cre-mediated deletion are susceptible to colitis and intestinal fibrosis, our finding may also be related to the deletion of Atg7 in CX3CR1+ intestinal macrophages." (PMID 32513210, 2020). "Furthermore, genetic association studies have suggested that LRRK2/MUC19 and ATG7 deficiency aggravate intestinal inflammation in a mouse model of colitis." (PMID 30669622, 2019). "Studies have shown that enteroepithelial‐specific Atg7 gene knockout mice (Atg7IEC‐KO) exhibited defective granule cell exocytosis and colitis symptoms." (PMID 40887825, 2025). "To delve deeper into the molecular mechanism through which Atg7 enhances colitis and controls the CD4+ T cells functions, we obtained naive CD4+ T cells derived from the spleen of Atg7ΔCD4 and Atg7fl/fl mice." (PMID 40887825, 2025). "Additionally, specific deletion of Atg7 in myeloid cells may increase susceptibility to colitis." (PMID 40887825, 2025). "In our study, we found that Atg7 deletion in CD4+ T cells aggravated colitis, suggesting the ATG7 functions as protective factor in T cell‐mediated immune regulation." (PMID 40887825, 2025). "As a consequence, we studied the role and mechanism of Atg7 in controlling CD4+ T cell differentiation as well as sustaining the gut environment balance in colitis mice." (PMID 40887825, 2025). "In colon epithelial conditional Atg7-KO mice, experimental colitis deteriorated, with more bacterial intrusion into the colonic epithelium." (PMID 38553562, 2024).
colitis (continued). "Having confirmed efficient deletion of Atg7 and disruption of autophagic flux in adipocytes, we next compared the effects of autophagy loss in adipocytes in steady‐state and DSS‐induced colitis." (PMID 36795015, 2023). "The functional role of Atg7-mediated autophagy in the pathogenesis of IBD was further analysed in experimental models of colitis." (PMID 22291845, 2012). "Besides, ATG7 was upregulated in CD4+ T cells at inflammatory loci in patients with colitis from single cell sequencing database (GSE226875)." (PMID 40887825, 2025). "However, the exact role of Atg7 expressed in CD4+ T cells in maintaining gut homeostasis during colitis continues to be explored." (PMID 40887825, 2025). "The findings are consistent with prior research showing that mice lacking Atg7 specifically in myeloid cells are at increased risk for experimental colitis." (PMID 40887825, 2025). "Moreover, another autophagy-deficient mouse model, ATG7 knockout mice, exhibited a diminished mucus layer and was more susceptible to dextran sulfate sodium (DSS)-induced colitis." (PMID 31213556, 2019). "Additionally, it is noteworthy that ATG7 is up‐regulated in A‐CD patients and experimental colitis mouse models, predominantly expressed in pro‐inflammatory CD4+IFNγ+ T cells, indicating that ATG7 affects the CD4+ T cells differentiation in the process of inflammation." (PMID 40887825, 2025). "In accordance, we found that lack of Atg7 in intestinal epithelial cells did not affect the intestinal pathology during DSS-induced colitis without SO." (PMID 32561763, 2020). "To elucidate the influence of Atg7 in CD4+ T cell immune responses of mucosal and colitis development, we generated Atg7 gene CD4+ T cell‐specific knockout mice (Atg7ΔCD4 mice) and examined the role of Atg7 on regulating differentiation of CD4+ T cell during colitis." (PMID 40887825, 2025).
colorectal cancer (16 papers, 2014 to 2025). A primary or metastatic malignant neoplasm that affects the colon or rectum. "In human colorectal cancer cells, celastrol triggers apoptosis and autophagy by inhibiting Nur79, leading to increased expression of Atg7 and activation of the Nur77/Atg7 signaling pathway." (PMID 39494324, 2024). "Further, we analyzed ATG7 levels in different subtypes of colorectal cancer and found ATG7 as the most highly expressed in MSI-H CRC patients." (PMID 38627815, 2024). "In order to further explore the prognostic implications associated with ATG7 and HMGCR expression patterns in colorectal cancer (CRC) patients, we utilized six different machine learning algorithm models to predict the incidence of 3-year survival events." (PMID 38627815, 2024). "In the present study, we used well-established immunocompetent mouse models of colorectal cancer to investigate the roles of ATG7 in immune response." (PMID 38627815, 2024). "In human colorectal cancer cell lines, similar autophagy promoting mechanisms, similar signaling proteins (ATG7, LC3, and LC3-II), and a similar resistance to Oxaliplatin and 5-FU was observed." (PMID 34761269, 2022). "Separate evidence shows that the expression of ATG5 and ATG7, autophagy-related proteins, influences the prognosis of colorectal cancer." (PMID 34484469, 2021). "DBT induced autophagic death of colorectal cancer cells through the upregulation of Atg7 and modulation of the mTOR/p70s6k signaling pathway." (PMID 29179457, 2017). "Previous studies reported that inhibition of autophagy by 3-methyladenine (3-MA) and Atg7 siRNA enhances 5-FU induced cytotoxicity in human colorectal cancer cells." (PMID 24900981, 2014). "The results suggested that focusing on the ATG7 gene or mitigating its kinase activity through discerning inhibitors could significantly influence the immunological milieu of colorectal cancer." (PMID 38627815, 2024). "Moreover, inhibition of ATG7 resulted in increased membrane expression of MHC-I on colorectal cancer cells." (PMID 38627815, 2024). "This implies that combining atorvastatin with ATG7 inhibition may potentiate the benefits of immunotherapy in colorectal cancer patients." (PMID 38627815, 2024). "This indicates that elevated ATG7 levels might contribute to the reduction in efficacy of immunotherapy in colorectal cancer." (PMID 38627815, 2024). "Additionally, the prognostic value of the ATG7-HMGCR axis in colorectal cancer patients was investigated by evaluating its expression patterns through machine learning algorithms for predicting the 3-year survival probability." (PMID 38627815, 2024). "Initially, a colorectal cancer tissue micro array, containing mucosa (n = 10), adenoma (n = 18) and adenocarcinoma (n = 49) spots, was stained for expression of essential autophagy proteins LC3b, Atg7, p62 and Beclin-1." (PMID 32046105, 2020). "In a further attempt to dissect Atg7 in the context of colorectal cancer, we demonstrated that a knockdown of Atg7 kills CRC cells via induction of classical apoptotic cell death utilizing the activation of Caspase 3 and the cleavage of PARP, a so far unreported phenotype." (PMID 32046105, 2020). "Taken together, this study suggests that inhibiting ATG7 can activate CD8+ T cells, which presents a novel mechanism for colorectal cancer (CRC) immunotherapy." (PMID 38627815, 2024). "DGBX decoction induces autophagic death of colorectal cancer cells and inhibits the growth of colorectal adenocarcinoma by regulating the mTOR/P70S6K signaling pathway and upregulating autophagy related protein 7 (Atg7)." (PMID 39210410, 2024). "miRNAs, which are regulators of autophagy, have also been reported to regulate autophagy, for example, the effect of miRNA and autophagy on colorectal cancer; miRNA-192-5p attenuates airway remodeling and autophagy in asthma by targeting MMP-16 and ATG7." (PMID 36388165, 2022).
colorectal cancer (continued). "In the present study, we found that BTG1 overexpression up-regulated the expression of ATG7, ATG14 and Beclin-1 in both colorectal cancer cells." (PMID 27447746, 2017). "Furthermore, we identified that ATG7 is a positive regulator of HMGCR, a target of statins that promote cholesterol accumulation in colorectal cancer." (PMID 38627815, 2024).
viral infection (16 papers, 2015 to 2025). "Particularly, function and underlying mechanisms of ATG7, an essential autophagy effector enzyme, in viral infections are largely unexplored, and little information is available about relationship between ATG7 and IAV pathogenesis." (PMID 38227600, 2024). "Silencing of ATG5 and ATG7 caused more severe disease symptoms and enhanced viral DNA accumulation compared to the control, and silencing of GAPCs reduced the severity of viral disease symptoms and viral DNA levels in plants infected by TYLCV or TYLCCNV." (PMID 28244873, 2017). "However, the functional repertoire and underlying mechanisms of ATG7 in viral infection and pathogenesis are largely unexplored." (PMID 38227600, 2024). "Further studies showed that Atg7 and Atg9 could contribute to the level of autophagy caused by viral infection." (PMID 29301200, 2017). "Further experiments demonstrated that PESP promotes autophagy by upregulating the transcription of ATG7, an essential effector enzyme for elongation of autophagosomal vesicles that plays a critical role in regulating viral infection and pathogenesis." (PMID 39137200, 2024). "It is of interest to evaluate the impact of ATG7 on the inflammatory response during viral infections, and to assess the role of GAPLINC in the regulation of inflammatory responses by ATG7 in the future." (PMID 38227600, 2024). "To verify this, we investigated the involvement of GAPLINC in suppression of IFN response by ATG7 during the virus infection." (PMID 38227600, 2024). "Consistently, the nuclear translocation of IRF3 was enhanced in ATG7 knockdown A549 cells compared with control cells following viral infection." (PMID 38227600, 2024). "We observed that the leaf curl symptoms caused by viral infection were much more severe and appeared 3 days earlier, and CLCuMuV DNA levels were significantly higher in ATG5- and ATG7- silenced plants compared to control plants." (PMID 28244873, 2017). "We used the K562 CML cell line in which a control shRNA (KS shCont) or a shRNA against the protein ATG7 (KS shATG7) were expressed through virus infection." (PMID 29228587, 2017). "These experiments unveil a new autophagy-independent mechanism by which ATG7 regulates viral infection via the GAPLINC-IRF3-IFN axis, which provides a understanding of how ATG7 can still influence the replication of IAV even when the cellular autophagy is blocked." (PMID 38227600, 2024). "This drove us to further evaluate effect of ATG7 on the activation of IRF3 upon viral infection." (PMID 38227600, 2024). "Loss of ATG7 rendered mice more resistant to IAV or PRV infection, as indicated by a lower degree of tissue injury, slower body weight loss, and an increased survival rate of ATG7 CKO mice after viral infection." (PMID 38227600, 2024). "Notably, our RNA-Seq analysis revealed that the expression levels of type I and III IFNs, which play central roles in restricting viral infections, were significantly increased in ATG7 knockdown A549 cells as compared to the control cells upon IAV infection." (PMID 38227600, 2024). "The expression level of the autophagy gene (ATG-5, ATG-7 and LC3) increased significantly after the virus infection." (PMID 39403204, 2024). "For example, the γb protein from BSMV and C2 from geminiviruses directly interact with ATG7, competitively interfering with the interaction between ATG7 and ATG8, thus subverting autophagy to promote viral infection." (PMID 37628763, 2023). "Recently, the γb protein of barley stripe mosaic virus (BSMV) was shown to competitively interfere with the interaction between ATG7 and ATG8 to subvert autophagy and promote viral infection." (PMID 37187544, 2023). "Facing viral infection, autophagy is activated with the aid of phosphorylated FoxO1 and Atg7, which promotes the development and function of NKT cells against viral infection." (PMID 36230955, 2022).
viral infection (continued). "Similarly, overexpression of ATG7 also resulted in enhanced H9N2 IAV replication, and a significant increase in SeV NP RNA levels in cells after the viral infection." (PMID 38227600, 2024). "However, γB, the VSR of barley stripe mosaic virus (BSMV), targeted AUTOPHAGY PROTEIN7 (ATG7) to disrupt the ATG7–ATG8 interaction and promote viral infection." (PMID 35216025, 2022). "This is the first study to clarify the role of TMEM39A in viral infection and also hints that there may be a interplay between TMEM39A and the ATG7-dependent autophagy pathway." (PMID 31849860, 2019). "In contrast, silencing of ATG5 or ATG7 did not affect viral infection." (PMID 29593293, 2018). "Furthermore, silencing of autophagy-related genes ATG5 and ATG7 reduced plant resistance to the DNA viruses CLCuMuV, Tomato yellow leaf curl virus, and Tomato yellow leaf curl China virus, whereas activating autophagy by silencing GAPC genes enhanced plant resistance to viral infection." (PMID 28244873, 2017).